GLP1R (glucagon like peptide 1 receptor)
Diseases named in the same sentence as GLP1R in open-access papers (continued):
Sharing a sentence is not in itself a finding about the gene and the disease.
congestive heart failure (10 papers, 2010 to 2025). Failure of the heart to pump a sufficient amount of blood to meet the needs of the body tissues, resulting in tissue congestion and edema. "Since a GLP-1R–ANP axis has been suggested in rodents, we aimed to investigate whether such an association between GLP-1R mediated hemodynamic effects and plasma ANP changes in patients with decompensated congestive heart failure, may take part." (PMID 26759609, 2016). "A study of patients with T2MD and congestive heart failure found that their levels of ANP were increased, whereas blood pressure was decreased, indicating that the GLP-1R-ANP axis is only active in patients with congestive heart failure." (PMID 34497589, 2021). "The magnitude of the benefit of GLP1R agonists on MACE was attenuated in patients with a younger age, with a body mass index less than 30, with a history of congestive heart failure, but the tests for interaction were not significant." (PMID 30223891, 2018). "Our exploratory finding that the magnitude of the benefit of GLP1R agonists on MACE was more remarkable in patients without a history of congestive heart failure but attenuated in patients with remain to be confirmed in future studies." (PMID 30223891, 2018). "Second, our finding that the magnitude of the benefit of GLP1R agonists on MACE was more remarkable in patients without a history of congestive heart failure but attenuated in patients with an only be considered exploratory and remain to be confirmed in future studies." (PMID 30223891, 2018).
hyperlipidemia (10 papers, 2015 to 2025). "This dual benefit positions GLP-1R agonists as a safer and more comprehensive treatment strategy for high-risk populations with T2DM and hyperlipidemia." (PMID 40711038, 2025).
mood disorder (10 papers, 2018 to 2025). A cognitive disorder a disturbance in which the person's mood is hypothesized to be the main underlying feature. "Our findings demonstrate that GLP1R perturbation is associated with a reduced risk of mood disorders." (PMID 40770700, 2025). "When accounting for all potential mechanisms, our results showed a significant association between decreased GLP1R levels and the reduced risk of mood disorders." (PMID 40770700, 2025). "To bridge this knowledge gap, we aimed to assess the causal effect of GLP1R perturbation on the risk of mood disorders (MDD and BD) using Mendelian randomization (MR)." (PMID 40770700, 2025). "In this study, we tested the hypothesis that GLP1R perturbation has a protective effect on the risk of mood disorders (MDD and BD) using plasma GLP1R levels and glycated hemoglobin (HbA1c) levels." (PMID 40770700, 2025). "Thus, our findings complement previous clinical observations and extend the evidence by providing a genetic-based causal inference of GLP1R involvement in mood disorders." (PMID 40770700, 2025). "Treatments targeting GLP1R, such as GLP1R agonists, may offer additional benefits for patients at risk of mood disorders." (PMID 40770700, 2025). "Moreover, this study provides insights into the potential protective effects of GLP1R perturbation in the risk of mood disorders." (PMID 40770700, 2025). "In this study, we explored the effects of GLP1R perturbation on mood disorders (MDD and BD) using genetic proxies." (PMID 40770700, 2025). "This study aimed to assess the effect of GLP1R perturbation on mood disorders based on protein and biomarker levels using Mendelian randomization (MR) approach." (PMID 40770700, 2025). "Our findings highlight the potential of GLP1R agonists, commonly used in metabolic disorders, as candidates for repurposing in mood disorders." (PMID 40770700, 2025). "Future research should incorporate clinical trial data and real-world evidence to evaluate the efficacy of GLP1R agonists in mood disorders." (PMID 40770700, 2025). "Glucagon-like peptide-1 receptor agonists have shown effects that extend beyond glucose regulation, impacting several neurobiological systems involved in mood disorders." (PMID 41010364, 2025). "In conclusion, this study provides insights into the potential protective effects of GLP1R perturbation in mood disorders." (PMID 40770700, 2025). "Our findings were consistent with previous studies that reported low serum GLP-1 levels and significant differences in GLP1R gene expression in patients with mood disorders." (PMID 40770700, 2025). "Another human study reported about abnormal gene expression of GLP-1R in post-mortem brain of individuals with mood disorder." (PMID 35754710, 2022). "Recent post mortem studies revealed that GLP-1R expression was downregulated in the dorsal lateral prefrontal cortex and hippocampus of patients suffering from mood disorders, and those changes further correlated with an elevated body mass index (BMI)." (PMID 34003475, 2021). "Therefore, human studies investigating the effects of GLP1R agonists on mood disorders are limited, whereas experimental studies and systematic reviews have provided evidence supporting this association." (PMID 40770700, 2025). "As shown in a post-mortem study, no abnormal gene expression of GLP-1R has been found in the brains of subjects with psychotic disorders, in contrast to the corresponding findings in patients with mood disorders." (PMID 36979648, 2023).
Wolfram syndrome (10 papers, 2016 to 2026). Wolfram syndrome (WS) also known as DIDMOAD, is a neurodegenerative disorder characterized by type I diabetes mellitus (DM), diabetes insipidus (DI), sensorineural deafness (D), bilateral optical atrophy (OA) and neurological signs. "For GLP-1R agonists to exert pleiotropic effects in Wolfram syndrome, the drugs should reach all affected tissues, including the brain." (PMID 36995380, 2023). "On the other hand, in dulaglutide-treated mice gliclazide and KCl, but not high glucose, stimulated insulin secretion, showing that GLP-1R agonists increase at least in part the function of beta cells from individuals affected by Wolfram syndrome." (PMID 36995380, 2023). "Exenatide hence improves mitochondrial function, reduces oxidative stress and protects WFS1-deficient iPSC-derived neurons from apoptosis, supporting the therapeutic potential of GLP-1R agonists to prevent cerebellar neurodegeneration in Wolfram syndrome." (PMID 36995380, 2023). "Sporadic clinical data on GLP-1R agonist use in people with Wolfram syndrome are accumulating." (PMID 36995380, 2023). "Exenatide and forskolin further improve mitochondrial function, reduce oxidative stress and prevent apoptosis in Wolfram iPSC-derived NPCs and cerebellar neurons, indicating that GLP-1R agonists have indeed therapeutic potential to prevent or delay neurodegeneration in Wolfram syndrome." (PMID 36995380, 2023). "Therefore, considering the unmet need of treatment for this orphan disease, we set out to test the therapeutic potential of GLP-1R agonists not only in WFS1-deficient mice, but also in human WFS1-deficient beta cells and neurons, and in a humanised mouse model of Wolfram syndrome." (PMID 36995380, 2023). "Our study provides novel evidence for the beneficial effect of GLP-1R agonists on WFS1-deficient human pancreatic beta cells and neurons, suggesting that these drugs may be considered as a treatment for individuals with Wolfram syndrome." (PMID 36995380, 2023). "In conclusion, we provide evidence for the beneficial impact of both short- and long-acting GLP-1R agonists in human pancreatic beta cells and neurons and humanised mice, thereby providing a strong preclinical basis to clinically test these drugs in people with Wolfram syndrome." (PMID 36995380, 2023).
Arrhythmia (9 papers, 2022 to 2025). Any cardiac rhythm other than the normal sinus rhythm. "In an extensive meta-analysis comprising >70,000 patients, GLP-1R agonists were usually not found to increase the risk of arrhythmia in diabetic patients." (PMID 39339176, 2024).
fibrosis (9 papers, 2016 to 2025). the formation of excess fibrous connective tissue in an organ or tissue in a reparative or reactive process. "As a momentary conclusion, survodutide, cotadutide, and efinopegdutide dual GLP-1R/GCGR co-agonists display potential benefits in MASH-related fibrosis and cirrhosis, while pemvidutide and mazdutide need more investigations in this area." (PMID 40004572, 2025). "First, we checked the expression of both GLP1R and GIPR in a public dataset (GEO accessions GSE135251) consisting of bulk RNA sequencing results from samples of patients with MASH at various fibrosis stages and healthy liver controls." (PMID 39607493, 2024). "Collectively, these findings suggest that acute GABABR/GLP-1R activation does not significantly modulate cardiac fibrosis progression after MI." (PMID 41244817, 2025).
malaise (9 papers, 2015 to 2025). A feeling of general discomfort or uneasiness, an out-of-sorts feeling. "The commonly reported side effect, nausea, appears less likely to influence the obtained data as the Ex4‐NAc shell dose and the Ex4‐IP dose do not alter kaolin intake, and the treatment protocols of the various GLP‐1R agonists have been adjusted to reduce the risk of malaise." (PMID 32770792, 2021). "The most plausible confounding factor is malaise, which is a common side effect of the GLP-1R agonists used." (PMID 37063267, 2023). "One of these is malaise, a common side effect by GLP-1R agonists, including semaglutide." (PMID 37295046, 2023). "One of the most common side effects reported for all GLP-1R agonists is malaise." (PMID 37063267, 2023).
MODY (9 papers, 2020 to 2025). "In addition, only MODY 3–5 have been reported to be treated with meglitinides, glucagon-like peptide-1 receptor agonists, sodium-glucose co-transporter-2 inhibitors, metformin, dipeptidyl peptidase-4 inhibitors, or repaglinide in case reports." (PMID 36573710, 2022). "To date, no cases of MODY 5 treated with glucagon-like peptide-1 receptor agonist (GLP-1RA) have been reported." (PMID 32871938, 2020).
nesidioblastosis (9 papers, 2012 to 2026). "The increased number of GLP-1R in Beta-cells is further potentiated by a considerable increase in number and size of the islets in this nesidioblastosis case." (PMID 31951592, 2020). "The molecular rationale for the positive 68Ga-DOTA-exendin-4 PET was found in the performed autoradiography study that demonstrated a more than 3-time higher density of GLP-1R in the islets of this nesidioblastosis patient when compared with islets of a normal pancreas." (PMID 31951592, 2020). "False positive scans may be due to nesidioblastosis, as it is found to also express GLP-1R." (PMID 37109517, 2023). "The density of GLP-1R was 3-fold higher in the islets of this nesidioblastosis patient as compared to that of normal pancreas islets implying that [Lys40-(Ahx-DOTA-68Ga)NH2] PET/CT may be a valuable tool in determining the surgical strategy also in nesidioblastosis which can be a focal disease." (PMID 31903131, 2020).
neuroblastoma (9 papers, 2013 to 2025). Neuroblastoma (NB) is the most common solid, extracranial childhood tumor. "Neurons in the hippocampus of the rat treated with GLP-1 or its analog, exendin-4, are more resistant to the excitotoxicity of glutamate, whereas GLP-1R overexpression increases the viability and proliferative capacity of human neuroblastoma cells." (PMID 40430434, 2025). "Reverse-transcription PCR (RT-PCR) and Western blotting techniques were used to detect the presence of GLP-1 receptor (GLP-1R) in SH-SY5Y human neuroblastoma cells." (PMID 33105690, 2020). "Notably, despite the fact that GLP-1R activation suppresses ER stress, Exendin-4 enhanced the expression of the ER stress-associated transcription factor ATF4 to protect H2O2-subjected neuroblastoma cells from death." (PMID 36117625, 2022). "The presence of the GLP-1R was verified, in accord with prior studies, on both SH-SY5Y human neuroblastoma cells and rat primary neurons by RT-RCR; GLP-1R mRNA possessed the expected RT–PCR product size of 190 bp." (PMID 24312624, 2013). "RT-PCR analysis showed mRNA expression of GLP-1R and glyceraldehyde-3-phosphate dehydrogenase (GAPDH; a housekeeping gene used for confirmation of the proper reactions) in DRG neurons and IFRS1 cells, as well as NSC-34 cells and ND7/23 mouse neuroblastoma/rat embryonic DRG neuron hybrid cells." (PMID 33804063, 2021).
acute pancreatitis (8 papers, 2018 to 2026). An acute inflammatory process that leads to necrosis of the pancreatic parenchyma. "Few incidences of acute pancreatitis have been reported during treatment with GLP-1R agonists apart from gastrointestinal side effects." (PMID 34577569, 2021). "Semaglutide, a long-acting glucagon-like peptide-1 receptor agonist (GLP-1 RA), has shown robust efficacy in glycemic control, weight reduction, and cardiovascular protection, but concerns remain regarding rare adverse events such as acute pancreatitis." (PMID 41728571, 2026).
chronic obstructive pulmonary disease (8 papers, 2019 to 2025). A chronic and progressive lung disorder characterized by the loss of elasticity of the bronchial tree and the air sacs, destruction of the air sacs wall, thickening of the bronchial wall, and mucous accumulation in the bronchial tree. "The results showed that GLP-1R agonists have therapeutic potential in the treatment of chronic obstructive pulmonary diseases by decreasing the severity of acute exacerbations." (PMID 37266425, 2023). "GLP-1 receptor (GLP-1R) agonists have been demonstrated to serve a pivotal role in the treatment of obstructive lung diseases, including chronic obstructive pulmonary disease (COPD)." (PMID 30836679, 2019). "Studies have shown that glucagon-like peptide-1 receptor agonists (GLP-1 RAs) provide lung benefits beyond glycemic control, including reduced risks of lung malignancy, pulmonary infection and chronic obstructive pulmonary disease exacerbations." (PMID 41083699, 2025).
diabetic ketoacidosis (8 papers, 2022 to 2026). The metabolic condition resulted from uncontrolled diabetes mellitus, in which the shift of acid-base status of the body toward the acid side because of loss of base or retention of acids other than carbonic acid is accompanied by the accumulation of ketone bodies in body tissues and fluids. "Moreover, a nationwide register-based cohort study from two countries found that the use of SGLT2 inhibitors compared with Glucagon Like Peptide-1 receptor agonists was associated with a 2.1-fold increased risk of diabetic ketoacidosis (95%CI 1.01–4.52) in T2DM patients." (PMID 35337085, 2022).
idiopathic intracranial hypertension (8 papers, 2023 to 2026). "Glucagon‐like peptide‐1 receptor (GLP‐1R) agonists, which lower cerebrospinal fluid (CSF) production, have shown success in idiopathic intracranial hypertension (IIH) by reducing ICP and improving headache frequency." (PMID 40542572, 2025). "GLP-1 is involved in migraine mechanisms and GLP-1R agonists are beneficial in individuals with idiopathic intracranial hypertension." (PMID 38997662, 2024). "The translational application of a glucagon-like peptide 1 receptor agonist for the treatment of raised intracranial pressure in idiopathic intracranial hypertension may be of significance as a potential countermeasure for SANS." (PMID 40607685, 2025).
intracranial hypertension (8 papers, 2023 to 2025). A finding characterized by increased cerebrospinal fluid pressure within the skull. "GLP-1R agonists have been shown to inhibit Na + K + ATPase-dependent secretion of cerebrospinal fluid at the choroid plexus, and the GLP-1R agonist exenatide has shown preliminary effectiveness for treating intracranial hypertension through this mechanism." (PMID 37362000, 2023). "Recent evidence highlights GLP‐1R agonists as potent agents in reducing ICP, significantly more effectively than traditional treatments for intracranial hypertension, such as acetazolamide or topiramate, and consistent with our findings, this effect is unrelated to weight loss." (PMID 40525593, 2025).
schizophrenia (8 papers, 2023 to 2025). A major psychotic disorder characterized by abnormalities in the perception or expression of reality. "This study suggests that genetically proxied activation of glucagon-like peptide-1 receptor is associated with a lower risk of schizophrenia." (PMID 40141382, 2025). "We found that genetically proxied GLP1R activation was associated with a reduced risk of schizophrenia and further mediation analysis suggests that this effect might not be related to glucose control but mediated by BMI." (PMID 40141382, 2025). "GLP1R is implicated in schizophrenia pathogenesis, and its agonists may exert potential benefits through weight management." (PMID 40141382, 2025). "This MR study suggests that the use of GLP1RA is associated with a reduced risk of schizophrenia, and the evidence from the animal models supports the potential of GLP1R as a therapeutic target for schizophrenia." (PMID 40141382, 2025). "In summary, these results provide compelling evidence that targeting GLP1R may have a positive impact on the clinical management of schizophrenia." (PMID 40141382, 2025).
colon carcinoma (7 papers, 2019 to 2026). "He Wenjing reported that GLP-1R expression was lacking in human colon cancer tissues and colon cancer cell lines." (PMID 39371922, 2024).
diabetic neuropathy (7 papers, 2018 to 2026). A chronic, pathological complication associated with diabetes mellitus, where nerve damages are incurred due to diabetic microvascular injury involving small blood vessels that supply these nerves, resulting in peripheral and/or autonomic nerve dysfunction. "Recent studies have demonstrated the efficacy of glucagon-like peptide-1 receptor agonists (GLP-1RAs) in managing neuropathic pain, commonly linked to diabetic neuropathy and various chronic pain disorders." (PMID 40427515, 2025). "The role of GLP-1R in neuropathic pain, particularly diabetic neuropathy, is supported by preclinical evidence." (PMID 38997662, 2024). "used high-glucose treatment in SH-SY5Y cells to mimic diabetic neuropathy and explored the effect of the GLP-1R agonist exendin-4 on diabetic neuropathy." (PMID 38313844, 2023). "Previous data demonstrated that activation of GLP-1R could alleviate neuropathic pain, cancer pain and diabetic neuropathy." (PMID 34325647, 2021).
irritable bowel syndrome (7 papers, 2018 to 2026). Irritable bowel syndrome (IBS) is a chronic functional condition of the lower gastrointestinal (GI) tract characterized by abdominal pain or discomfort and disordered bowel habit (diarrhea, constipation, or fluctuation between the two). "Additionally, GLP-1R agonists reduce visceral hypersensitivity and ameliorate symptoms in patients with irritable bowel syndrome." (PMID 38997662, 2024).
lung carcinoma (7 papers, 2012 to 2025). "The recent findings underscore the potential of SGLT-2 inhibitors, especially in combination with glucagon-like peptide-1 receptor agonists (GLP-1), to improve survival outcomes in lung cancer patients with type 2 diabetes." (PMID 41234538, 2025). "The associations of three relatively new classes of anti-diabetic medications–glucagon-like peptide-1 receptor agonists (GLP-1RA), dipeptidyl peptidase 4 inhibitors (DPP-4I), and sodium-glucose cotransporter 2 inhibitors (SGLT-2I) with lung cancer prognosis remain unclear." (PMID 40040724, 2025).